CDKN2A (cyclin dependent kinase inhibitor 2A)
Diseases named in the same sentence as CDKN2A in open-access papers (continued):
Sharing a sentence is not in itself a finding about the gene and the disease.
diabetes (continued). "To further understand the functional relevance of Cdkn2a-mediated beige adipocyte maintenance in obesity and its related diabetes, we challenged the control and Cdkn2aUcp1 KO mice with a HFHS diet for 120 days during the rewarming period following cold exposure." (PMID 37169793, 2023). "The main negative risk factors that denote aggression and lead to increased mortality were identified as follows: comorbidities of patients (hypertension and diabetes mellitus or hyperglycemia), type of surgical resection, degree of cell differentiation, and alterations of the CDKN2A gene." (PMID 36136867, 2022). "CDKN2A/B highly expressed in pancreas is considered as a strong determinant of diabetes mellitus." (PMID 34925466, 2021). "After multivariable adjustment, Nrf2 expression remained significantly and negatively associated with CDKN2A expression (β coefficient=-1.51, P=0.01), independent of chronological age, gender, race, and diabetes status." (PMID 32661200, 2020). "Though CDKN2A/2B was reported to influence diabetes risk across varied ethnicities, not many studies have replicated the association of the CDKN2A/2B variant rs7020996 with T2D." (PMID 33017871, 2020). "We also demonstrated that the negative association between Nrf2 and CDKN2A expression was independent of chronological age, gender, race, diabetes status, and inflammatory markers." (PMID 32661200, 2020). "Further, we observed a marked increase in CDKN2A level with the increase in duration of diabetes." (PMID 32280716, 2020). "For example, mutations in Slc38a3 cause overall developmental delay, intellectual disability, hypotonia, and loss of speech, Adamts5 prevents impaired cardiac function by regulating versican degradation, and Cdkn2a/b locus influences the risk of diabetes through both islet and non-islet mechanisms." (PMID 37305038, 2023). "Abnormal CDKN2A/2B gene expression could lead to pancreatic hypoplasia and diabetes." (PMID 34418317, 2021). "The negative association between Nrf2 and CDKN2A expression remained statistically significant even after additionally accounting for the variable significant at P<0.1 in the univariable analysis (i.e., diabetes) (β coefficient=-1.51, P=0.010, in Model 2)." (PMID 32661200, 2020). "Mice expressing a constitutively active Cdk4 that cannot bind its inhibitor p16INK4a, a product of the CDKN2A locus, were protected from obesity and diabetes." (PMID 37395281, 2023). "Studies have reported that the expression of cyclin-dependent kinase inhibitor 2A (CDKN2A), has a relationship with diabetes and hypertension." (PMID 36523663, 2022). "Published studies on peripheral blood cells in diabetes, cardiac diseases and cancers showed the regulatory effect of CDKN2B-AS1 on the expression of CDKN2A and CDKN2B transcripts." (PMID 32825664, 2020). "Our analysis revealed a distinct stratification: while TRPC1, SELENOP, CDKN2A, GSN, and PGR all showed significant dysregulation in UCEC tissues compared to normal endometrium, only SELENOP, CDKN2A, and PGR exhibited diabetes-specific modifications in UCEC patients." (PMID 41244925, 2025). "Furthermore, stratification of UCEC patients by diabetic status revealed that the dysregulation of SELENOP, CDKN2A, and PGR was specifically exacerbated by diabetes." (PMID 41244925, 2025). "In this study, we studied whether diabetes influences the clinico-pathological profile and methylation status of CDH1 and CDKN2A genes in patients with PDC." (PMID 29273724, 2017). "This is thought to be due to the CDKN2A and CDKN2B genes in this genomic region inhibiting CDK4 and CDK6, which has been demonstrated to influence β cell proliferation and mass, eventually leading to diabetes." (PMID 25430018, 2014).
diabetes (continued). "The associations of 23 SNPs located within 17 candidate genes (MTHFR, PPARγ, LPL, INSIG, TCF7L2, FTO, KCNJ11, JAZF1, CDKN2A/B, ADIPOQ, WFS1, CDKAL1, IGF2BP2, KCNQ1, MTNR1B, IRS1, ACE) with overweight and obesity, diabetes, metabolic phenotypes, and MetS were examined in both studies." (PMID 24959828, 2014). "For example, CDKN2A and CDKN2B have been identified in diabetes GWA studies, suggesting that cell cycle arrest or some other unknown function of these genes plays a role in Type 2 diabetes." (PMID 23840313, 2013). "Since only a single PDC case with short-DM (1/17 cases, 6%) showed promoter methylation of CDH1 or none for CDKN2A in non-neoplastic tissues, it is likely that the presence of long-term diabetes may be a major trigger for the epigenetic alterations of tumor suppressor genes." (PMID 29273724, 2017). "In this study, we evaluated the methylation status of CDH1 and CDKN2A promoters in PDC tissues and non-neoplastic tissues obtained from patients with or without diabetes and explored to clarify whether diabetes influences tumor behavior and prognosis of the patients." (PMID 29273724, 2017).
non-small cell lung carcinoma (68 papers, 1999 to 2025). A group of at least three distinct histological types of lung cancer, including non-small cell squamous cell carcinoma, adenocarcinoma, and large cell carcinoma. "Compared to peritoneal mesothelioma, MPM harbour more frequent loss of CDKN2A, and loss of CDKN2A has been linked to resistance to immunotherapy in non-small cell lung cancer." (PMID 35637530, 2022). "Palbociclib has also exhibited encouraging results against patients with liposarcoma and CDKN2A-mutated non-small cell lung cancer." (PMID 36139498, 2022). "The previous study reported that the loss of CDKN2A significantly made non-small cell lung cancer patients experience disease progression after immune checkpoint blockade therapy." (PMID 36052076, 2022). "Palbociclib showed promising activity in patients with CDKN2A-mutated non-small-cell lung cancer." (PMID 36765923, 2023). "However, Cdkn2a inactivation increased tumor number in the KRAS G12D context more than in KRAS G12C, consistent with genomic analyses of human non-small cell lung cancers describing enrichment of CDKN2A mutations in tumor with KRAS G12D relative to KRAS G12C or other KRAS variants." (PMID 37828026, 2023). "Interestingly, patients with CDKN2A mutations in our cohort were more likely to experience disease progression during treatment and, consequently, had significantly poorer OS, consistent with observations in other cancers, such as non-small cell lung cancer (NSCLC)." (PMID 40141436, 2025). "A carcinoid subtype in which SMARCA4, KRAS, FGF3/4/19, STK11, CDKN2A/B, and other genomic alterations predominate in non-small cell lung cancer-like subtypes." (PMID 40661782, 2025). "Studies have reported that CDKN2A methylation is an independent indicator of poor prognosis in patients with non-small cell lung cancer (NSCLC)." (PMID 36937524, 2023). "This is because palbociclib, a CDK4/6 inhibitor, showed an anti-tumor effect in patients with non-small cell lung cancer and CDKN2A alterations." (PMID 36119486, 2022). "Homozygous deletion (HD) of the tumor suppressor gene CDKN2A is the most frequent genetic alteration in malignant pleural mesothelioma and is also frequent in non-small cell lung cancers." (PMID 34249754, 2021). "Recently, it was reported that genetic inactivation of Cdkn2a by CRISPR/Cas9 promoted lung metastasis of mouse with non-small cell lung carcinoma transplanted subcutaneously." (PMID 35004325, 2021). "CDKN2A methylation and/or p16 expression has been shown to have prognostic value in non-small cell lung cancer (NSCLC), bladder cancer, and head and neck (H&N) cancers." (PMID 32314030, 2020). "The deletion of the CDKN2A copy number was the most frequent CNV that occurred in seven CSF ctDNA samples from six non-small cell lung cancers (6/22, 27.3%)." (PMID 32711494, 2020). "CDKN2A level is previously demonstrated as an independent prognostic factor in non-small cell lung carcinoma." (PMID 26858029, 2016). "In conclusion, we identified significant associations between seven genes (CDKN2A, RASSF1, MGMT, RARB, DAPK, WIF1 and FHIT) and smoking behavior in non-small cell lung cancer patients." (PMID 25754026, 2015).
non-small cell lung carcinoma (continued). "Alterations of CDKN2A are also common in NSCLC (non-small cell lung cancer)." (PMID 35456025, 2022). "The underlying reason of the increased expression of CD274 and PDCD1LG2 in ATC with CDKN2A loss is not unveiled in this study, but their potential relationship in non-small cell lung cancer were previously reported." (PMID 31235699, 2019). "Low ARF expression without deleterious mutations in the CDKN2a locus is found in non-small cell lung cancer (NSCLC), implying that post-translational regulation of ARF may be involved in cancer development." (PMID 32759846, 2020). "For instance, bladder cancer patients had elevated promoter methylation of RASSF1, CDH1, DAPK, and CDKN2A genes, which was distinct from hypermethylated genes MGMT, FHIT, and hMLH1 found in NSCLC (Non-Small Cell Lung Cancer) patients." (PMID 36672415, 2023). "Recent evidence regarding non-small cell lung cancer suggests that co-alterations in EGFR and CDKN2A may enhance oncogenicity and reshape the immune microenvironment." (PMID 41463200, 2025). "In some rare cases associated with non-small-cell lung cancer and some other cancers MTAP loss occurred in absence of CDKN2A deletion." (PMID 36572880, 2022). "Whilst an association between smoking and CDKN2A inactivation has not previously been identified in OSCC, a meta-analysis in non-small cell lung carcinoma (NSCLC) has reported a positive association between p16 promoter methylation and smoking." (PMID 33804510, 2021). "In particular, hypermethylation of PIK3R5, CDKN2A and two retinoid X receptors (RXRG and RXRG) occurred in a non-redundant manner in the non small cell lung cancer subtypes (Z score=2.82, empirical P<0.01)." (PMID 28581523, 2017).
familial melanoma (66 papers, 2004 to 2025). Familial melanoma (FM) is a rare inherited form of melanoma characterized by development of histologically confirmed melanoma in two first degrees relatives or more relatives in an affected family. "CDKN2A is a highly penetrant gene associated to familial melanomas, being responsible of up to 40% of the cases." (PMID 40869905, 2025). "CDKN2A, in particular, is one of the most well-studied genes associated with familial melanoma and plays a critical role in regulating the cell cycle by encoding proteins p16INK4A and p14ARF, both of which are tumor suppressors." (PMID 39518584, 2024). "Considering CDKN2A is the major susceptibility gene in familial melanoma but is only mutated in around 20–40% of families worldwide, half of the patients included were CDKN2A wild-type." (PMID 34660619, 2021). "We identified a gene profile associated with familial melanoma independently of CDKN2A germline status." (PMID 34660619, 2021). "Germline mutations in cyclin-dependent kinase inhibitor 2A (CDKN2A), a kinase that plays a role in UV-induced melanin production by encoding two different tumor suppressor genes, p16INK4a and p14ARF, are associated with familial melanoma." (PMID 27999823, 2016). "Altered baseline expression signatures associated with CDKN2A mutations in cultured normal skin fibroblasts from familial melanoma patients have already been reported." (PMID 24742402, 2014). "Familial melanoma (FM) is a dominantly heritable cancer that is associated with mutations in the tumor suppressor CDKN2A/p16." (PMID 23371019, 2013). "A similar finding was previously reported in familial melanoma, with CDKN2A as well as BRAF and NRAS mutations." (PMID 22039425, 2011). "p16 is encoded at the locus most commonly mutated in familial melanoma, CDKN2A, underlining its importance in melanoma." (PMID 21418545, 2011). "The majority of the germline mutations reported for familial melanoma are present in CDKN2A exon 2 and impact most of the time on both proteins." (PMID 24281082, 2010). "While the CDKN2A gene remains the primary high-penetrance locus associated with familial melanoma, several recent studies have revealed the presence of additional non-CDKN2A germline variants that may be implicated in individual susceptibility." (PMID 40558591, 2025). "In addition to familial melanoma, CDKN2A germline mutations have been also associated with an elevated risk of pancreatic, lung, and other tobacco-related cancers." (PMID 40869905, 2025). "The germline CDKN2A R24Q variant is associated with familial melanoma." (PMID 40340749, 2025). "Moreover, oncogene Cyclin‐dependent kinase 4 (CDK4) and TSG CDKN2A, which encodes p16INK4a, have been linked with familial melanoma progress." (PMID 40761498, 2025). "Similarly, CDK4, a proto-oncogene facilitating G1-to-S phase transition, and its inhibitor p16INK4a (encoded by CDKN2A) are critical in familial melanoma." (PMID 39859464, 2025). "High penetrance genes associated with familial melanoma are CDKN2A and CDK4." (PMID 37895483, 2023). "CDKN2A is the major high-risk susceptibility gene identified thus far for familial melanoma." (PMID 31203567, 2019). "Approximately 25% of these familial cases can be explained by germline mutations in cyclin-dependent kinase inhibitor 2A (CDKN2A), the most frequent gene mutated in familial melanoma, revealing that the genetic explanation for the majority of cases remains elusive." (PMID 25874698, 2015). "Worldwide, approximately 20-40% of kins with familial melanoma harbour germline mutations in the CDKN2A gene, located on chromosome 9p21, which encodes two different proteins, p16INK4 and p14ARF, both involved in regulation of cell cycle progression and induction of senescence." (PMID 22759494, 2012).
familial melanoma (continued). "This condition is more frequently observed in patients with genetic predispositions, such as mutations in CDKN2A and CDK4, which are commonly associated with familial melanoma." (PMID 39518584, 2024). "Although the CDKN2A and CDK4 genes have been primarily linked to familial melanoma, the contribution of these genes only accounts for a small percentage of familial melanoma." (PMID 38275910, 2024). "The most common alteration in familial melanoma involves the CDKN2A locus, which is altered in about 20–40% of familial melanoma cases." (PMID 36834954, 2023). "Germline alterations in the CDKN2A (p16INK4a/p14ARF) gene are responsible for familial melanoma–pancreatic cancer syndrome." (PMID 38201484, 2023). "A NanoString miRNA array was applied to plasma-derived sEV samples of a cohort of 36 patients including sporadic metastatic melanoma patients, unaffected, and affected familial melanoma (CDKN2A/p16 gene alteration carriers) patients and healthy controls." (PMID 35804857, 2022). "Accordingly, primary melanocyte-keratinocyte co-cultures were established from the healthy skin biopsies of 16 unrelated familial melanoma patients (8 CDKN2A mutant, 8 CDKN2A wild-type) and 7 healthy controls." (PMID 34660619, 2021). "There have been reports of CDKN2A E69G in familial melanoma patients with 30% decreased binding to CDK4 compared with its wild type." (PMID 30709382, 2019). "The CDKN2A gene is located in the 9p21 locus and represents currently the main high-risk gene predisposing to CMM, firstly assigned in familial melanoma in early nineties." (PMID 31382929, 2019). "The cyclin-dependent kinase inhibitor 2A gene (CDKN2A) is the familial melanoma locus (located on the short arm of chromosome 9) that controls two tumor suppressor proteins (p14-ARF and p16-INK4A) with major roles in cell proliferation and senescence." (PMID 29795011, 2018). "Finally, given that different histopathological subtypes of MPM and familial melanoma possess variable behavior via their molecular signatures, the algorithm must be correctly interpreted in relation to CDKN2A homozygous deletion." (PMID 38667459, 2024). "In addition, mutations in genes such as cyclin-dependent kinase inhibitor 2A (CDKN2A) and cyclin-dependent kinase 4 (CDK4) have been shown to be the most common genetic variants in familial melanoma." (PMID 37427124, 2023). "The aim of the present study was to investigate the global molecular effect of germinal CDKN2A mutations (p.G101W) and MC1R RHC variants in the transcriptome of primary skin cells from individuals belonging to skin cancer prone families (familial melanoma pedigrees)." (PMID 24742402, 2014). "In particular, germline mutations convey pro-tumorigenic features and often affect the high-risk susceptibility genes CDKN2A and, less commonly, CDK4, associated with familial melanoma, where the phenotype of CDKN2A or CDK4-mutated families is indistinguishable." (PMID 34123788, 2021). "On the other hand, the 10 cases identified as carrying homo- and heterozygous deletions of CDKN2A were segregated into 7 cases of MPM (70%) and 3 individuals with familial melanoma (FM, 30%)." (PMID 38667459, 2024). "The most important high penetrance gene is the cyclin-dependent kinase Inhibitor 2A (CDKN2A), responsible for about 30% of all familial melanoma cases." (PMID 29523635, 2018). "A miRNA array was generated in plasma-derived exosomes from familial melanoma patients (CDKN2A/p16 gene carriers), nonfamilial melanoma patients and healthy control subjects." (PMID 34544412, 2021).